RNU6-666P (RNA, U6 small nuclear 666, pseudogene)
Gene: Small nuclear RNA gene on chromosome 10 (27,315,120 to 27,315,226, forward strand). Ensembl gene ENSG00000200369.
Homologues: Orthologues: dog U6 (68% identical), pig U6 (65% identical), rabbit U6 (65% identical), rabbit U6 (60% identical). Paralogues in human: RNU6-452P (94% identical), RNU6-811P (89% identical), RNU6-1207P (88% identical), RNU6-1293P (87% identical), RNU6-156P (87% identical), RNU6-458P (86% identical), U6 (86% identical), RNU6-1132P (85% identical), RNU6-614P (85% identical), RNU6-1210P (84% identical), RNU6-721P (84% identical), U6 (84% identical), and 1284 more.